RNU6-271P (RNA, U6 small nuclear 271, pseudogene)
Gene: Small nuclear RNA gene on chromosome 10 (96,112,747 to 96,112,851, forward strand). Ensembl gene ENSG00000200728.
Homologues: Orthologues: chimpanzee U6 (99% identical), mouse Gm23355 (94% identical), mouse Gm24713 (94% identical), mouse Gm25448 (94% identical), dog U6 (92% identical), guinea pig U6 (90% identical), rat LOC120096741 (88% identical), pig U6 (85% identical). Paralogues in human: RNU6-12P (95% identical), RNU6-13P (95% identical), RNU6-32P (95% identical), RNU6-1 (94% identical), RNU6-17P (94% identical), RNU6-18P (94% identical), RNU6-2 (94% identical), RNU6-3P (94% identical), RNU6-45P (94% identical), RNU6-4P (94% identical), RNU6-5P (94% identical), RNU6-6P (94% identical), and 1286 more.